EPSTI1 (epithelial stromal interaction 1)
Description:
Plays a role in M1 macrophage polarization and is required for the proper regulation of gene expression during M1 versus M2 macrophage differentiation (By similarity). Might play a role in RELA/p65 and STAT1 phosphorylation and nuclear localization upon activation of macrophages (By similarity).
Synonyms: BRESI1; MGC29634
Tractability: PROTAC: ubiquitination databases record sites on it; its protein half-life has been measured.
Gene: Protein-coding gene on chromosome 13 (42,886,388 to 42,992,392, reverse strand). Ensembl gene ENSG00000133106.
Pathways (Reactome):
Signal Transduction: RND1 GTPase cycle
Genetic constraint (gnomAD): Loss-of-function variants: 44 observed, 35.56 expected, observed/expected ratio (o/e) 1.24, 90% interval 0.97 to 1.59. The upper end of that interval is the gene's LOEUF score, 1.59, which puts it in group 6 of 6, group 1 being the genes least tolerant of losing a copy. Missense variants: 312 observed, 298.51 expected, observed/expected ratio (o/e) 1.05, 90% interval 0.95 to 1.15. Synonymous variants: 112 observed, 110.46 expected, observed/expected ratio (o/e) 1.01, 90% interval 0.87 to 1.19.
Homologues: Orthologues: chimpanzee EPSTI1 (98% identical), macaque EPSTI1 (92% identical), rabbit EPSTI1 (78% identical), dog EPSTI1 (70% identical), pig EPSTI1 (68% identical), mouse Epsti1 (66% identical), rat Epsti1 (65% identical), tropical clawed frog epsti1 (33% identical), zebrafish epsti1 (32% identical), zebrafish zgc:194621 (12% identical).
Diseases named in the same sentence as EPSTI1 in open-access papers:
EPSTI1 is named in the same sentence as 35 diseases in open-access papers, as found by Europe PMC text mining. Sharing a sentence is not in itself a finding about the gene and the disease. The quoted sentences say what the papers report.
breast cancer (18 papers, 2015 to 2025). A primary or metastatic malignant neoplasm involving the breast. "The association of EPSTI1 induction of invasion in breast cancer cells was attributed to the increased expression of Slug and Twist mRNA and increased expression of fibronectin and α2β1 integrins." (PMID 33970103, 2021). "The association of EPSTI1 with tumor metastatic potential is supported by observations that EPSTI1 is highly upregulated in invasive breast cancer tissues and suggested the role of EPSTI1 in promoting metastasis, tumorsphere formation, and stemness." (PMID 33970103, 2021). "EPSTI1 (Epithelial Stromal Interaction 1) was initially discovered in breast cancer and is involved in epithelial-mesenchymal transition (EMT), inflammation, and immune regulation." (PMID 40519934, 2025). "Epithelial-stromal interaction 1 (EPSTI1) is first identified through its increased gene expression in breast cancer epithelial cells when cocultured with stromal fibroblasts and is known as an interferon response gene." (PMID 38993551, 2024). "EPSTI1 (epithelial stromal interaction 1) is an interferon (IFN) inducible gene which has been found as a stromal fibroblast-induced gene in breast cancer and also highly upregulated in invasive breast carcinomas as compared to normal breast." (PMID 38935691, 2024). "KLF8 induces breast cancer (BC) invasion through the epithelial-stromal interaction 1/valosin-containing protein/NF-κB signaling pathway, which results in the degradation of IκBα and subsequent activation of NF-κB in the nucleus." (PMID 36761967, 2023). "miR-654-5p blocks the growth of breast cancer cells by specifically targeting EPSTI1, demonstrating its potential as a treatment target." (PMID 36567857, 2022). "When compared with healthy breast tissue, the level of EPSTI1 expression is considerably elevated in invasive breast cancer tissues." (PMID 36567857, 2022). "Although the aberrant expression of EPSTI1 in breast cancer cells is well-established, there is little indication in the literature on the role of EPSTI1 to induce EMT, cancer invasion, and metastasis." (PMID 33970103, 2021). "EPSTI1 was identified as a stromal fibroblast-induced gene upon co-cultures of breast cancer cells with stomal fibroblasts." (PMID 33970103, 2021). "EPSTI1 for breast cancer, AR for prostate cancer, GRAP for oral squamous cell carcinoma, CDCP1 and PLAGL2 for ovarian cancer were the only five direct targets identified for miR‐654‐5p thus far." (PMID 33135351, 2020). "Epithelial stromal interaction protein 1 (EPSTI1) is a 37 kDa protein that was first identified in human breast cancer cells." (PMID 28694743, 2017). "In this work, we functionally characterize two breast cancer associated genes, the proteasome 26S subunit ATPase 3 interacting protein (PSMC3IP) and the epithelial-stromal interaction 1 (EPSTI1), to explore their potential apoptotic role in breast cancer." (PMID 25590583, 2015). "We explore the anti-apoptotic role of PSMC3IP and EPSTI1 and their contribution in breast cancer development." (PMID 25590583, 2015). "Overview of the results obtained from apoptosis-related functional assays upon modulation of EPSTI1 expression in breast cancer cells." (PMID 25590583, 2015). "EPSTI1 has also been shown to be essential for ovarian cancer and breast cancer." (PMID 39107958, 2024). "Similarly, miR-654-5p can target Epithelial Stromal Interaction 1 to weaken breast cancer cell proliferation and invasion while promoting cell apoptosis." (PMID 37777559, 2023). "EPSTI1 has been found to be related to breast cancer, oral squamous cell carcinoma (OSCC) and lung squamous cell carcinoma (LSCC), which may link COVID-19 to what has been found in the complication of mammograms." (PMID 36298522, 2022). "EPSTI1, mapped to chromosome 13q13.3, is initially reported as a stromal fibroblast-induced gene in human breast cancer and highly upregulated in tumor tissues of breast cancer patients." (PMID 30572883, 2018).
breast cancer (continued). "Based on the generated interaction network, we examine several apoptotic markers to determine the effect of PSMC3IP and EPSTI1 gene expression modulation in two different human breast cancer cell lines to suggest potential molecular mechanisms to unveil their role in the disease." (PMID 25590583, 2015). "EPSTI1 (epithelial-stromal interaction 1) is upregulated in tissues characterized by extensive epithelial-stromal interaction, which promotes invasion and metastasis of breast cancer." (PMID 26146465, 2015). "Epithelial stromal interaction 1 (EPSTI1, probeID: cg03753191) is an interferon (IFN)-responsive gene that was originally isolated from mixed cultured human breast cancer cells and fibroblasts." (PMID 35620480, 2022). "On the other hand, EPSTI1, an interferon (IFN) response gene, has been identified as a stromal fibroblast-induced gene in breast cancer, being highly upregulated in invasive breast carcinomas as compared with normal breast." (PMID 25590583, 2015). "EPSTI1, initially identified as an induced gene in a three-dimensional tumor environment assay, was reported to promote epithelial-mesenchymal transition (EMT) and tumor metastasis in breast cancer." (PMID 36330510, 2022). "EPSTI1 expression is related to the onset and migration, stem cell-like characteristics, epithelial–mesenchymal transition (EMT) as well as the invasion and metastasis of breast cancer cells." (PMID 36567857, 2022).
COVID-19 (15 papers, 2020 to 2024). A disease caused by infection with severe acute respiratory syndrome coronavirus 2. "Moreover, another two genes, IFI27 (encoding interferon alpha-inducible protein 27, mitochondrial) and EPSTI1 (encoding epithelial-stromal interaction protein 1), have numerous strong correlations with the genes in the target pathway of COVID-19." (PMID 38096046, 2024). "However, the expression and function of circRNAs derived from the EPSTI1 gene in COVID-19 are still chiefly unknown." (PMID 36081604, 2022). "Previous research has highlighted the up-regulation of genes such as IFI44L, IFFI44, RSAD2, OAS1, EPSTI1, and OSAL in COVID-19, contributing to immune regulation." (PMID 38601162, 2024). "This phenomenon reflects the discussions in the Introduction that RIPK3 is related to the natural essence of COVID-19, while ATP6V1B2, IFI27, BTN3A1, SERTAD4, and EPSTI1 contain more information about SARS-CoV-2." (PMID 36298522, 2022). "Important gene combinations in the white blood cells of patients with COVID-19, including IFIT3, OASL, USP18, XAF1, IFI27, and EPSTI1, can be used for its diagnosis." (PMID 35928229, 2022). "In upper airway samples and blood leukocytes of SARS‐CoV‐2‐infected patients, it has been reported that EPSTI1 is significantly overexpressed compared to patients without SARS‐CoV‐2 infection, and could have a helpful effect on antiviral therapy in COVID-19." (PMID 36081604, 2022).
ovarian carcinoma (4 papers, 2019 to 2024). A malignant neoplasm originating from the surface ovarian epithelium. "We detected the expression of EPSTI1 and found that EPSTI1 was also overexpressed in ovarian cancer tissues." (PMID 30887698, 2019). "In summary, circEPSTI1 regulated EPSTI1 expression and ovarian cancer progression by sponging miR‐942." (PMID 30887698, 2019).
autoimmune disease (3 papers, 2018 to 2025). A disorder resulting from loss of function or tissue destruction of an organ or multiple organs, arising from humoral or cellular immune responses of the individual to their own tissue constituents. "EPSTI1 has also been implicated in immune response, as it promotes the expression of viral response genes and is associated with immune privilege and autoimmune diseases." (PMID 39869563, 2025). "EPSTI1 regulates B cell proliferation and activation through the NF‐KB pathway, resulting in autoimmune disease." (PMID 38020713, 2023).
colon cancer (3 papers, 2021 to 2024). "We sought to determine the functional relevance of KSR1-dependent induction of EPSTI1 to phenotypic plasticity in colon cancer cells." (PMID 33970103, 2021). "To determine the extent to which KSR1- and ERK-dependent EPSTI1 translation is critical to colon tumor cell growth and invasion, we expressed a MSCV-FLAG-EPSTI1-GFP construct in KSR1-CRISPR knockout HCT116, SW480, and HCT15 cells." (PMID 33970103, 2021). "We observed that EPSTI1 protein is aberrantly expressed in colon cancer cell lines HCT116 and HCT15, while its expression is detected weakly in HCECs." (PMID 33970103, 2021). "The experiment showed that KSR1 increases the levels of a protein called EPSTI1, which colon cancer cells need to transform into migratory cells." (PMID 33970103, 2021). "To determine the regulation of EPSTI1 in human colon tumor maintenance, we performed siRNA knockdown of EPSTI1 in HCT116 and HCT15 cells." (PMID 33970103, 2021). "However, further investigation is needed to reveal how EPSTI1 is generated and how this protein helps colon cancer cells move and invade other tissues." (PMID 33970103, 2021). "EPSTI1 is both necessary and sufficient for coordinating the upregulation of N-cadherin with the downregulation of E-cadherin to stimulate cell motility and invasion in colon cancer cells." (PMID 33970103, 2021). "Considering the suggested role of EPSTI1 in promoting EMT-like phenotypes, we sought to evaluate the biological role of EPSTI1 in colon cancer cells." (PMID 33970103, 2021).
systemic lupus erythematosus (3 papers, 2018 to 2024). An autoimmune multi-organ disease typically associated with vasculopathy and autoantibody production. "As evidence of its potential utility, this approach identified methotrexate, a lupus therapy, targeting EPSTI1." (PMID 34946847, 2021). "Epsti1 upregulation was also noted in systemic lupus erythematosus and rheumatoid arthritis patients." (PMID 30347820, 2018).
virus infection (3 papers, 2016 to 2025). "Notably, several miRNAs, such as gga-miR-12243-3p and gga-miR-6701-3p, both targeting EPSTI1, have been previously implicated in immune responses to viral infections." (PMID 41042757, 2025). "Our results with SINV infection also revealed different inhibitory mechanisms, with some proteins targeting the early stages of virus infection (e.g. UBE2L6), and others participating throughout the course of infection (e.g. EPSTI1)." (PMID 40204275, 2025). "In particular, 8 genes (Mx1, EPSTI1, XAF1, IFI44L, GBP1, SAMD9, SAMD9L, and CMPK2) were expressed in the highly resistant cell lines HPAF-II and Hs766T but not the highly permissive cell lines MIA PaCa-2 and Capan-1 in the absence of virus infection." (PMID 27533247, 2016).
breast tumor (2 papers, 2010 to 2021). "EPSTI1 is expressed at low levels in normal breast and colon tissue but aberrantly expressed in breast tumor tissue." (PMID 33970103, 2021). "EPSTI1 promotes cell invasion and malignant growth of primary breast tumor cells." (PMID 33970103, 2021).
colorectal cancer (2 papers, 2019 to 2021). A primary or metastatic malignant neoplasm that affects the colon or rectum. "EPSTI1 is overexpressed in human colorectal cancer (CRC) cells." (PMID 33970103, 2021). "Among the top 10 deregulated genes, MMP2 (Matrix Metallopeptidase 2) is well known for its role in colorectal cancer invasion and EPSTI1 (Epithelial stromal interaction 1) and MPO (Myeloperoxidase) are related to tumor development." (PMID 30987352, 2019).
primary Sjogren syndrome (2 papers, 2018 to 2023). "Cxcl9, Ccl19 and Epsti1 have been implicated in Sjögren syndrome in humans or animal models." (PMID 30347820, 2018). "EPSTI1 was highly expressed in peripheral blood and B cells in labial gland tissue from primary Sjogren syndrome." (PMID 38020713, 2023). "Of the other disease-relevant genes identified in our study, Epsti1 was upregulated in patients with Sjögren syndrome." (PMID 30347820, 2018).
prostate carcinoma (2 papers, 2016 to 2020). A carcinoma that arises from epithelial cells of the prostate gland. "Similarly, the genes EPSTI1 and PHF11 (also part of the 21 gene group) localize to chromosome 13 and are co-deleted in ~15% of prostate cancer patients." (PMID 27366948, 2016).
atherosclerosis (1 paper, 2025). A disease characterized by the build-up of fatty material and calcium deposition in the arterial wall resulting in partial or complete occlusion of the arterial lumen. "Epithelial-stromal interaction 1 (EPSTI1; >2.7-fold), which is involved in monocyte-endothelial cell adhesion, is associated with increased atherosclerosis plaques." (PMID 41205594, 2025).
Cachexia (1 paper, 2024). Severe weight loss, wasting of muscle, loss of appetite, and general debility related to a chronic disease. "Consistently, Epsti1-deficient mice exhibit more severe muscle wasting in the cancer cachexia model, strongly underscoring Epsti1 as an important modulator of inflammatory responses in muscle maintenance." (PMID 38993551, 2024). "Furthermore, in a cancer-cachexia model, Epsti1 deficiency resulted in exacerbated muscle wasting accompanied by excessive inflammation." (PMID 38993551, 2024). "In summary, our data demonstrate that Epsti1 plays a critical role in muscle regeneration and the prevention of cachexia-induced muscle wasting through limiting inflammatory responses by modulation of the VCP/STAT1 axis." (PMID 38993551, 2024). "However, the body weights of Epsti1 KO cachectic mice were lower than that of WT cachectic mice after 24 days, suggesting an early onset of cachexia-induced muscle wasting." (PMID 38993551, 2024).
dacryoadenitis (1 paper, 2018). Inflammation and enlargement of the lacrimal gland. "Thus, type I IFN signaling contributed to the male-specific upregulation of disease-relevant genes (Cxcl9, Ccl19, Epsti1) and was required for dacryoadenitis development in male NOD mice." (PMID 30347820, 2018). "We found that upregulation of Cxcl9, Ccl19 and Epsti1 was altered in NOD mice deficient in type I IFN signaling and these mice also failed to develop dacryoadenitis." (PMID 30347820, 2018). "While Treg-depletion was not sufficient to drive dacryoadenitis in castrated male NOD mice, chemokines (Cxcl9, Ccl19) and other potentially disease-relevant genes (Epsti1, Ubd) were upregulated in male lacrimal glands." (PMID 30347820, 2018).
dermatomyositis (1 paper, 2022). Dermatomyositis (DM) is a type of idiopathic inflammatory myopathy characterized by evocative skin lesions and symmetrical proximal muscle weakness. "RNA-Seq transcriptome comparison of polymyositis and dermatomyositis has shown dermatomyositis-specific increases in OASL, EPSTI1, and IFI27 within CD8 + T cells." (PMID 34997119, 2022).
hepatoma (1 paper, 2015). "There were two hepatoma cell lines, Huh7.5 and HLCZ01, that were used for investigating the mechanisms of IL-28A and EPSTI1 to inhibit HCV propagation in our study." (PMID 26146465, 2015).
influenza (1 paper, 2019). An acute viral infection of the respiratory tract, occurring in isolated cases, in epidemics, or in pandemics; it is caused by serologically different strains of viruses (influenzaviruses) designated A, B, and C, has a 3-day incubation period, and usually lasts for 3 to 10 days. "In this study, the expression level of EPSTI1 has increased in the influenza-infected subjects versus normal cases." (PMID 31665046, 2019).
Lewis lung carcinoma (1 paper, 2024). "To validate this hypothesis, we induced cachexia by injection of Lewis lung carcinoma (LLC) cells into WT and Epsti1 KO mice." (PMID 38993551, 2024).
melanoma (1 paper, 2023). A malignant, usually aggressive tumor composed of atypical, neoplastic melanocytes. "CYTH4, DENND1C, AOAH, TBC1D10C, EPSTI1, GIMAP7, and FASL (FAS ligand) were novel predictors of ICB therapy and displayed high level of correlations with multiple immune checkpoints in melanoma and across 30 human cancers." (PMID 36588164, 2023). "In addition to melanoma, CYTH4, AOAH, DENND1C, TBC1D10C, EPSTI1, SERPINB8, and GIMAP7 stratify responders and non-responders to ICB in other cancer types." (PMID 36588164, 2023).
metastatic melanoma (1 paper, 2023). A melanoma that has spread from its primary site to another anatomic site. "CYTH4, DENND1C, AOAH, EPSTI1, and TBC1D10C expressions are upregulated in metastatic melanoma compared to primary tumors." (PMID 36588164, 2023).
triple-negative breast carcinoma (1 paper, 2015). An invasive breast carcinoma which is negative for expression of estrogen receptor (ER), progesterone receptor (PR), and human epidermal growth factor receptor 2 (HER2). "Our results show that PSMC3IP and EPSTI1 are able to modulate the extrinsic apoptotic pathway in estrogen receptor positive and triple negative breast cancer cell lines, highlighting them as potential therapeutic targets." (PMID 25590583, 2015).